ROCK1 (Rho associated coiled-coil containing protein kinase 1)
Diseases named in the same sentence as ROCK1 in open-access papers (continued):
Sharing a sentence is not in itself a finding about the gene and the disease.
melanoma (23 papers, 2010 to 2025). A malignant, usually aggressive tumor composed of atypical, neoplastic melanocytes. "Non-metabolism-related proteins (BRCA1, phosphorylase B kinase regulatory subunit: PHKA1, tyrosine-protein kinase receptor: ALK and rho-associated protein kinase: ROCK1) correlated to melanoma development differed among all groups." (PMID 34199079, 2021). "Third, the possible effects of BRAF mutation on the miR-335/ROCK1 axis need further illumination due to the frequent BRAF V600E in melanoma." (PMID 32219065, 2020). "ROCK1 is known to regulate the switch toward amoeboid motility, and this round morphology has been associated to enhanced aggressiveness and motility of melanoma cells." (PMID 25538140, 2014). "Yin and colleagues demonstrated that this circ_0001591 sponges miR-431-5p, resulting in the upregulation of the ROCK1/PI3K/AKT pathway, and this is associated with cell growth and invasion in melanoma cell lines." (PMID 40869968, 2025). "ROCK inhibitors also overcome targeted therapy resistance: Y-27632, GSK269962A, or fasudil restore BRAF inhibitor efficacy in melanoma, and ROCK1 silencing sensitizes BRAF/NRAS-mutant cells to MAPK inhibitors." (PMID 40368918, 2025). "Immunohistochemistry on aggressive/advanced melanoma tissues from 129 patients also showed a down-regulation of Rho kinase signaling with decreased expression of ROCK1." (PMID 37683138, 2023). "A previous study has proven Y-27632, a ROCK1 inhibitor can promote the growth and migration of human melanoma cells in vivo." (PMID 37683138, 2023). "Circ 0001591 upregulates ROCK1 expression by binding to miR-431-5p and promotes malignant progression of melanoma by regulating the ROCK1/PI3K/AKT signaling pathway." (PMID 36034860, 2022). "As we found several RhoGEFs and ROCK1/2 to be increased during melanoma progression, we first investigated which proteins were binding RhoA in melanoma cells." (PMID 34172930, 2021). "We found that the expression of ROCK1 in melanoma tissues increased significantly compared to that in adjacent tissues." (PMID 32219065, 2020). "We demonstrate here that in melanoma ROCK1/2-Myosin II also plays an important pro-tumourigenic role via cell autonomous mechanisms." (PMID 33082334, 2020). "Our results suggest that ROCK1/2-Myosin II activity in amoeboid melanoma cells controls both tumour growth and spread." (PMID 33082334, 2020). "miR-335 declined significantly in melanoma and directly targeted the widely expressed ROCK1 in melanoma." (PMID 32219065, 2020). "Briefly, the present findings gained insights into miR-335/ROCK1-mediated radiosensitivity and provided a promising therapeutic strategy for improving radiotherapy against melanoma." (PMID 32219065, 2020). "We propose here that non-canonical WNT11/5B-FZD7-DAAM1 axis crucially and specifically controls tumour initiation potential in melanoma by promoting ROCK1/2-Myosin II driven amoeboid proliferative and invasive phenotype." (PMID 33082334, 2020). "Currently, the validated connection between miR-335/ROCK1 and radioresistance broadened the miR-335/ROCK1-mediated networks in the development of refractory melanoma." (PMID 32219065, 2020). "ROCK1 mediated the occurrence and development of melanoma in various ways, and obstruction of ROCK1 inhibited the proliferation and migration of melanoma cells." (PMID 32219065, 2020). "The present study demonstrated that the downregulation of miR-335 led to radioresistance via suppressing ROCK1 in melanoma, expanding the understanding of miRNA-mediated radioresistance in the generally radioresistant skin cancer." (PMID 32219065, 2020). "Consistent with the prediction of STARBASE and miRDB database, miR-335 targeted ROCK1 via binding with 3′-UTR of ROCK1 directly, resulting in attenuation of proliferation, migration, and radioresistance of melanoma cells." (PMID 32219065, 2020). "In conclusion, the present study demonstrated that miR-335 decreased in melanoma and targeted ROCK1." (PMID 32219065, 2020).
melanoma (continued). "This suggests that ROCK1/2-Myosin II activity plays a crucial role in all steps of melanoma progression." (PMID 33082334, 2020). "In the current study, we use potent and selective ROCKi to demonstrate that ROCK1/2-Myosin II axis is an important regulator of tumour growth and metastasis in melanoma." (PMID 33082334, 2020). "By integrating our functional genomic and (phospho)proteomic data, we identified ROCK1 as a potential drug target for BRAF mutant melanoma." (PMID 25538140, 2014). "Taking the data of both shRNA screens together, and integrating them with our proteomic analysis results, yielded the serine threonine kinase ROCK1 as an interesting and potential drug co-target in melanoma therapy." (PMID 25538140, 2014). "By combining our genomic data with (phospho)proteomic analyses, we were able to identify a new target, ROCK1, whose inhibition rendered melanoma cells much more sensitive to BRAF/MAPK inhibition." (PMID 25538140, 2014). "ROCK1 silencing increased melanoma cell elimination when combined with BRAF or ERK inhibitor treatment." (PMID 25538140, 2014). "However, glucocorticoids can promote migration, invasion, and metastasis of melanoma by activating the ROCK1/2, indicating the role of ROCK1 in SKCM was still unclear." (PMID 37683138, 2023). "Although inhibiting a single target gene, such as ROCK1 and NGFR, can sensitize vemurafenib-resistant melanoma cells, our results showed that pair-wise perturbation of ROCK1 + NF2 or NGFR + NF2 conferred a strong protective phenotype during vemurafenib treatment." (PMID 34106558, 2021). "The lncRNA X-inactive specific transcript (XIST) is overexpressed in melanoma and regulates the following miRNA-mRNA axes: miR-23a-3p/GINS complex subunit 2 (GINS2) and 139-5p/Rho associated coiled-coil containing protein kinase 1 (ROCK1)." (PMID 34638331, 2021). "Therefore, miR-335 disturbed proliferation and migration, while promoting radiosensitivity of melanoma by inhibiting ROCK1." (PMID 32219065, 2020). "The present study revealed that miR-335 upregulated in melanoma and targeted ROCK1." (PMID 32219065, 2020). "Interestingly, inhibition of ROCK (using Y27632), a downstream target of RHOA signalling, also induces CDKN1A in melanoma, and ROCK1 has been identified as a potential candidate for combinatorial therapy with BRAF inhibitors." (PMID 27835901, 2016). "In these studies inhibition of ROCK1 sensitises melanoma cells to PLX-4720." (PMID 27835901, 2016). "ROCK1 supports migration, invasivity and lymph node metastasis of melanoma cells." (PMID 20424615, 2010). "However, this aspect may be somewhat tissue-dependent, as, for example, in non-small cell lung cancer and melanoma, only targeting both ROCK1/ROCK2 was able to prevent tumor growth." (PMID 35406401, 2022). "Furthermore, ROCK1 is PD‐L1 co‐expressed gene in melanoma patients." (PMID 33587338, 2021). "Importantly, we also find that amoeboid melanoma cells express EMT-related genes driven by ROCK1/2." (PMID 33082334, 2020). "Studies have shown that silencing ROCK1 via genetic modulation or inhibition with GSK269962A (a selective ROCK1 inhibitor) enhances the effectiveness of BRAF and MAPK inhibitors against BRAF and NRAS mutant melanoma cells." (PMID 39273383, 2024). "Our findings support the role of ALK, ROCK1 and PHKA1 as a protein kinase for activating the metabolism of the energy sources from macronutrients used by the melanoma to support growth, proliferation and survival." (PMID 34199079, 2021). "Lactate secretion cooperation to promote melanoma metastasis via phosphorylation enzyme is involved in the pathway for PHKA1 and lipid metabolism, as well as glucose metabolism for ROCK1." (PMID 34199079, 2021). "While PLX4720 treatment influenced ROCK1 signaling, silencing of ROCK1 as well as the use of a pharmacologic ROCK inhibitor significantly increased the elimination of melanoma cells by PLX4720 and SCH772984 treatments." (PMID 25538140, 2014).
melanoma (continued). "In line with this, we found an inverse correlation between ROCK1/2 and PIG3 levels in melanoma." (PMID 26464464, 2016). "Three days post-seeding into the wells, the migratory forefronts of non-targeting shRNA endothelial cells and the melanoma cells had collided, while the forefronts of ROCK1 or 2 knockdown cells were 670 +/- 80 and 920 +/- 110 μm apart, respectively." (PMID 22934846, 2013).
Obesity (22 papers, 2015 to 2025). Accumulation of substantial excess body fat. "Increased NEAT1 sponges miR-146a-5p, thus releasing its inhibition on ROCK1, a kinase that promotes obesity-associated MASLD." (PMID 39872125, 2024). "Diet-induced and genetic forms (db/db and ob/ob) of obesity were associated with reduced ROCK1 activity in murine hypothalamic neurons." (PMID 35769086, 2022). "ROCK1 also interferes with insulin signaling to increase blood glucose levels and ROCK1 overactivity is associated with metabolic disease states and related comorbidities including obesity, insulin resistance, and dyslipidemia." (PMID 33633690, 2020). "In addition, liver ROCK1 activation caused by obesity was reported to inhibit AMPK activity, leading to the increase of SREBP-1c mediated lipogenesis pathway, thus driving liver lipid accumulation." (PMID 34305621, 2021). "Disentangling the mechanisms underlying the prevention of obesity through ROCK1 deficiency will provide further insight into critical aspects of cell biology, and might also lead to personalized medicine options for the treatment or prevention of NAFLD." (PMID 30919598, 2019). "We generated a mouse with muscle-specific, constitutively active ROCK1 and this mouse develops obesity and insulin resistance, suggesting two separate mechanisms are responsible for insulin resistance: 1) ROCK1 is activated by Rho A or Rho E causing PKC activation and suppressed glycogenesis." (PMID 27411515, 2016). "Finally, it is unclear why hepatic ROCK1 deficiency prevents HFD‐induced obesity in mice." (PMID 30919598, 2019). "Reports have already shown that ANKRD12, NEXN, IFT74, and ROCK1 play an important role in adipose deposition or obesity." (PMID 38474122, 2024). "Rho-kinase 1 (ROCK1) is a known driver of HFD/obesity-induced hepatic steatosis via stimulation of de novo lipogenesis." (PMID 39872125, 2024). "Knockdown of ROCK1 expression in healthy mice led not only to excessive food intake, dyslipidemia, and obesity, but also hyperleptinemia (leptin is an effective adipokine) (Landry, Shookster & Huang, 2021)." (PMID 37304877, 2023). "Deletion of ROCK1 in the ARH results in impaired leptin sensitivity, increased food intake, and severe obesity, highlighting ROCK1 as a critical modulator of leptin’s action on energy homeostasis." (PMID 38027481, 2023). "Dysregulation of ROCK1 signaling has been found in several metabolic syndrome‐related diseases, including obesity and type 2 diabetes." (PMID 30919598, 2019). "In that model, jointly overexpressing a dominant-negative ROCK1 and 2 rescued diet-induced obesity and improved glucose tolerance, which contrasts with the findings in mice expressing only the dominant negative ROCK2 or lacking ROCK1." (PMID 31075957, 2019). "We studied mice with muscle-specific ROCK1 activity (mCaROCK1) because these mice generally develop insulin resistance and obesity." (PMID 27411515, 2016). "In studying mice with muscle-specific constitutive ROCK1 activation (mCaROCK1), we found that irisin production was down-regulated and the mice developed obesity and insulin resistance." (PMID 27411515, 2016). "Specific deletion of ROCK1, a downstream kinase of the CD44/ankyrin/Cdc42 signaling pathway, attenuated obesity-associated insulin resistance in adipose tissue, indicating a role in obesity-related metabolic syndromes." (PMID 37894408, 2023). "It is noteworthy that different from adipose tissues where ROCK2 appears to the major isoform contributing to ROCK activity, ROCK1 is reportedly the major isoform in liver and mediating diet-induced obesity and insulin resistance through the ROCK1/AMPK signaling pathway." (PMID 35769086, 2022). "In addition, ROCK1 activity is significantly reduced in the skeletal muscle of human subjects with obesity and type 2 diabetes." (PMID 34443331, 2021).
Obesity (continued). "Mechanistically, ROCK1 directly mediates leptin signaling and impairs ghrelin signaling through unknown mechanisms and the importance of these functions is underscored by obesity manifesting when hypothalamic ROCK1 function is impaired." (PMID 33633690, 2020). "Further supporting the hypothesis that overactive ROCK1 is involved in metabolic disease pathologies, at least in mice, constitutively active skeletal muscle-specific ROCK1 (SM-CA-ROCK1) results in early-onset obesity, even when eating a normal diet." (PMID 33633690, 2020). "Furthermore, hypothalamic ROCK1 knockout in healthy mice results in excessive food intake, dyslipidemia, and obesity, while ROCK1 overexpression has opposite effects." (PMID 33633690, 2020). "Looking at lipid metabolism in the liver of bodyweight‐matched L‐ROCK1−/− mice and control mice fed with a HFD, the authors concluded that hepatic ROCK1 plays a pivotal role in obesity‐induced hepatic steatosis through upregulation of lipogenesis‐related genes that promote hepatic DNL." (PMID 30919598, 2019). "Although we were not allowed to get enough tissues to isolate hADSC from MSL patients, our findings suggest that the RhoA/ROCK1/ERK1/2 signaling pathway is a potential therapeutic target for the development of drugs that prevent or treat MSL or obesity patients." (PMID 26148871, 2015). "In addition, mice lacking ROCK1 in pro-opiomelanocortin and agouti-related protein neurons, which are mediators of leptin action, displayed obesity and impaired leptin sensitivity associated with increased food intake, reduced energy expenditure and locomotor activity." (PMID 35769086, 2022). "As partial deletion of ROCK1 or ROCK2 has been found to attenuate high-fat-diet obesity-induced insulin resistance, the use of Y27632 in patients suffering from obesity could be a strategy to decrease AdEV release and reduce cardiovascular diseases associated with obesity." (PMID 33670146, 2021). "Similarly, ROCK1 deletion in POMC neurons leads to POMC hypoactivity and obesity due to reduced locomotor activity, while whole-ARC ROCK1 deletion has even greater effects." (PMID 33633690, 2020). "However, ROCK-1 disruption in these neuronal populations only induces mild obesity as compared to the massive obesity observed in mice lacking LEPR in ARC GABAergic neurons." (PMID 26578907, 2015). "Nonspecific ROCK1 inhibitors fasudil and Y-27632 demonstrate inhibitor pharmacotherapy is beneficial for these diseases; however, adverse effects such as hypotension, insulin resistance, and obesity are observed when ROCK expression/activity is non-specifically altered or systemically downregulated." (PMID 33633690, 2020).
non-small cell lung carcinoma (21 papers, 2014 to 2022). A group of at least three distinct histological types of lung cancer, including non-small cell squamous cell carcinoma, adenocarcinoma, and large cell carcinoma. "miR-335 inhibited TGF-β1-induced epithelial–stromal transformation of non-small cell lung cancer (NSCLC) through Rho-associated kinase 1 (ROCK1)." (PMID 32219065, 2020). "FPPS can mediate the epithelial-mesenchymal transition (EMT) and invasion of TGF-β1-induced non-small cell lung cancer cells via RhoA/ROCK1 signaling pathway." (PMID 34486491, 2021). "Overall, our results demonstrated that non-small-cell lung cancer viability is regulated by ROCK1 and the LATS2-JNK pathway." (PMID 32554853, 2020). "In line with this reasoning, Rock1 overexpression has been reported in 73.3% of non-small cell lung cancer samples." (PMID 29899821, 2018). "In non-small cell lung carcinoma, suppression of ROCK1 or ROCK2 expression alone was sufficient to impair anchorage-independent growth." (PMID 26725045, 2016). "For instance, experiments in non-small cell lung carcinoma cells showed that the tumor suppressor roles of miR-135a, miR-148b and miR-335-5p are exerted through modulation of expression of ROCK1." (PMID 36177350, 2022). "For instance, PSMG3-AS1 via down-regulation of miR-340 and subsequent up-regulation of ROCK1 could promote cell migration and invasion of non-small cell lung carcinoma." (PMID 36177350, 2022). "For example, KCNMB2-AS1 increases Rho associated coiled-coil containing protein kinase 1 (ROCK1) expression via binding with miR-374a-3p, therefore promoting cell proliferation, migration, and invasion and inhibiting cell apoptosis in non-small-cell lung cancer." (PMID 34516362, 2021). "Accordingly, while the loss of either Rock1 or Rock2 had no negative impact on tumorigenesis in mouse models of non-small cell lung cancer and melanoma, loss of both blocked tumor formation, as no tumors arise in which both Rock1 and Rock2 have been genetically deleted." (PMID 26765561, 2016). "Activation of ROCK1 signaling pathway has been proven to promote invasion and metastasis of pancreatic cancer cells and ROCK1 may inhibit the PTEN/FAK pathway to promote the development of non-small-cell lung cancer." (PMID 32507765, 2020).